CPS1 (carbamoyl-phosphate synthase 1)
Description:
Involved in the urea cycle of ureotelic animals where the enzyme plays an important role in removing excess ammonia from the cell.
Synonyms: GATD6; CPS1D; CPSASE1; PHN
Tractability: Small molecule: an approved drug acts on it; a structure with a bound ligand is known; a high-quality ligand is known; it has a high-quality binding pocket; it belongs to a druggable protein family. Antibody: UniProt places it where antibodies can reach, with high confidence; its Gene Ontology location is reachable by antibodies, with medium confidence. PROTAC: ubiquitination databases record sites on it; its protein half-life has been measured; a small molecule that binds it is known.
Target class: Enzyme; Ligase
Gene: Protein-coding gene on chromosome 2 (210,477,682 to 210,679,107, forward strand). Ensembl gene ENSG00000021826.
Subcellular location: Mitochondrion; Nucleus, nucleolus; Cell membrane
Subcellular location (Human Protein Atlas): Nucleoli; Nucleoli rim; Mid piece; Principal piece
Pathways (Reactome):
Disease: CPS1 variants cause CPS1 deficiency
Metabolism: Urea cycle
Gene Ontology:
Molecular function: carbamoyl-phosphate synthase (ammonia) activity; metal ion binding; modified amino acid binding; potassium ion binding; protein binding; small molecule binding; carbamoyl-phosphate synthase (glutamine-hydrolyzing) activity; ATP binding; calcium ion binding; endopeptidase activity; glutamate binding; phospholipid binding; protein-containing complex binding
Biological process: carbamoyl phosphate biosynthetic process; cellular response to ammonium ion; homocysteine metabolic process; nitric oxide metabolic process; response to lipopolysaccharide; triglyceride catabolic process; vasodilation; citrulline biosynthetic process; glutamine metabolic process; urea cycle; 'de novo' pyrimidine nucleobase biosynthetic process; cellular response to cAMP; cellular response to fibroblast growth factor stimulus; cellular response to glucagon stimulus; cellular response to oleic acid; hepatocyte differentiation; liver development; midgut development; monoatomic anion homeostasis; organophosphate biosynthetic process; response to alcohol; response to amine; response to amino acid; response to cAMP; response to dexamethasone; and 10 more
Cellular component: mitochondrial nucleoid; mitochondrion; nucleolus; mitochondrial matrix; plasma membrane; cytosol; mitochondrial inner membrane; protein-containing complex
Genetic constraint (gnomAD): Loss-of-function variants: 94 observed, 145.96 expected, observed/expected ratio (o/e) 0.64, 90% interval 0.54 to 0.76. The upper end of that interval is the gene's LOEUF score, 0.76, which puts it in group 3 of 6, group 1 being the genes least tolerant of losing a copy. Missense variants: 1,539 observed, 1,738.3 expected, observed/expected ratio (o/e) 0.89, 90% interval 0.85 to 0.92. Synonymous variants: 576 observed, 605.78 expected, observed/expected ratio (o/e) 0.95, 90% interval 0.89 to 1.02.
Gene-disease validity (ClinGen):
ClinGen rates the evidence that CPS1 causes each of these diseases.
carbamoyl phosphate synthetase I deficiency disease (autosomal recessive): Definitive.
Homologues: Orthologues: chimpanzee CPS1 (99% identical), macaque CPS1 (99% identical), dog CPS1 (96% identical), rabbit CPS1 (96% identical), pig CPS1 (96% identical), rat Cps1 (96% identical), mouse Cps1 (95% identical), guinea pig CPS1 (93% identical), tropical clawed frog cps1 (79% identical), zebrafish cps1 (72% identical). Paralogues in human: CAD (50% identical), OTC (6% identical).
Diseases named in the same sentence as CPS1 in open-access papers:
CPS1 is named in the same sentence as 163 diseases in open-access papers, as found by Europe PMC text mining. Sharing a sentence is not in itself a finding about the gene and the disease. The quoted sentences say what the papers report.
Hyperammonemia (45 papers, 2009 to 2025). An increased concentration of ammonia in the blood. "Carbamoyl phosphate synthetase 1 (CPS1) deficiency, a urea-cycle disorder, results in hyperammonemia initiating a sequence of adverse events that can lead to coma and death if not treated rapidly." (PMID 40083646, 2025). "Enzyme deficiencies within the urea cycle, exemplified by CPS1, can lead to a notable buildup of ammonia in the blood, a condition known as hyperammonemia." (PMID 40052303, 2025). "Over the course of 3 weeks after initiating Cps1 genomic recombination, hyperammonemia and hyperglutaminemia ensue, with weight loss, sarcopenia, derangement of amino acids and, ultimately, death." (PMID 40421838, 2025). "Mice with induced deficiency in hepatic CPS1 develop hyperammonemia within 4 weeks of induction and die." (PMID 38535834, 2024). "This is the first study to report hyperammonemia in a CPS1 deficiency patient due to an infection after LT." (PMID 38235270, 2024). "Carbamoyl-phosphate synthetase 1 (CPS1) deficiency is an autosomal recessive congenital urea cycle disorder (UCD) characterized by hyperammonemia." (PMID 38235270, 2024). "Noteworthy clinical manifestations, including hyperammonemia, are evident in individuals with CPS1 deficiency." (PMID 39129920, 2024). "For example, germline mutation of the CPS1 gene causes CPS1 deficiency, a rare lethal urea cycle disorder with autosomal recessive inheritance, causing the death of newborns owing to hyperammonemia." (PMID 37443694, 2023). "Individuals with a CPS1 deficiency typically present hyperammonemia with a wide range of clinical manifestations, including migraine, abdominal pain, vomiting, and decreased urea production." (PMID 37306871, 2023). "Cornerstones of treatment for UCD, including CPS1 deficiency and other inherited disorders with hyperammonemia, are restriction of dietary protein intake, scavenging ammonia drugs, and orthotopic liver transplantation." (PMID 36064721, 2022). "Carbamoylphosphate synthetase 1 (CPS1) deficiency is a rare inborn error of metabolism leading often to neonatal onset hyperammonemia with coma and high mortality." (PMID 32154057, 2020). "C/EBPα‐deficient mice lack CPS1 expression and exhibit hyperammonemia, indicating that C/EBPα is essential for CPS1 expression." (PMID 28557353, 2017). "Carbamoyl phosphate synthetase 1 (CPS1) catalyzes the first reaction wherein ammonia and bicarbonate combine to form carbamoyl phosphate, and mice deficient in Cps1 suffered pronounced hyperammonemia and neonatal lethality." (PMID 26075008, 2015). "CPS1 mutations are known to cause carbamoylphosphate synthetase I deficiency, an autosomal recessive inborn error of metabolism of the urea cycle which causes hyperammonemia." (PMID 25569235, 2015). "These structures allow rationalizing the effects of mutations found in patients with CPS1 deficiency (presenting hyperammonemia, mental retardation and even death), as exemplified here for some mutations." (PMID 26592762, 2015). "Additionally, CPS1 is a key enzyme in nitrogen metabolism, and mutations in CPS1 have been linked to urea cycle disorders, hyperammonemia, and impaired metabolic function." (PMID 40077791, 2025). "An OTC-deficient male and a CPS1-deficient female survived from episodes of hyperammonemia." (PMID 32934962, 2020). "Clinically, patients with hyperammonemia caused by genetic CPS1 deficiency often have several pathological syndromes such as encephalopathy, coma, and intellectual disability, suggesting that CPS1 is important for ammonia detoxification." (PMID 32029232, 2020). "CPS1 deficiency caused by CPS1 gene mutation usually leads to accumulation of ammonia in the blood and thereby presents severe hyperammonemia, which is neurotoxic resulting in neonatal death or severe and irreversible brain damage in the developing and mature brain." (PMID 31507628, 2019).
Hyperammonemia (continued). "The association between common variants in CPS1 and glycine might therefore be driven by mild forms of genetically induced Hyperammonemia." (PMID 26352407, 2015). "Whether CPS1 mutations and hyperammonemia are a correlative, causative, or contributing phenomenon has not been elucidated." (PMID 25605237, 2015). "CPS1 deficiency can lead to high ammonia levels in the body (Hyperammonemia, OMIM #237300)." (PMID 26352407, 2015). "CPS1 deficiency may lead to altered alanine and glycine in response to hyperammonemia." (PMID 40421838, 2025). "Thus, patients with CPS1 deficiency should be aware of the development of hyperammonemia after LT." (PMID 38235270, 2024). "In addition to inhibiting aberrantly expressed CPS1 in tumor cells, AT067-H09 and H3B-120 could inhibit hepatic CPS1 and block the urea cycle leading to hyperammonemia, which can cause irreversible brain injury." (PMID 37047726, 2023). "Deficiencies in urea cycle enzymes (UCEs), such as carbamoyl phosphate synthetase 1 (CPS1), can result in hyperammonemia, leading to severe neurological deficits." (PMID 40052303, 2025). "Long-term survival (9 months, end of study) with ammonia control was achieved in AAV8.CPS1-administered Cps1flox/flox mice, while all null vector-injected controls died with marked hyperammonemia; female mice demonstrated improved survival over treated males." (PMID 40083646, 2025). "To advance new therapeutic approaches and understand the effects of chronic hyperammonemia on the developing nervous system, we sought to develop a Cps1 hypomorph." (PMID 40421838, 2025). "This mitochondrial disorder shares several clinical features with UCDs, particularly carbamoylphosphate synthetase 1 (CPS1) deficiency and N-acetylglutamate synthase (NAGS) deficiency, most notably the presence of hyperammonemia." (PMID 40862046, 2025). "Although the unmet need is high, and traditional treatment options for preventing hyperammonemia are limited, preclinical results for CPS1 gene therapy suggest some promise." (PMID 40421838, 2025). "In order to probe the effect of hyperammonemia on the developing nervous system and explore new therapies, a murine Cps1 exon 3-4 mutant was previously generated." (PMID 40421838, 2025). "Increased O-GlcNAcylation on specific threonine residues enhances the catalytic activity of CPS1, thus promoting ureagenesis during hyperammonemia." (PMID 36768465, 2023). "The consequent accumulation of methylmalonic-CoA results in the competitive inhibition of N-acetylglutamate synthase and carbamoyl phosphate synthase 1 (CPS 1), an enzyme involved in the first and rate-limiting step of the urea cycle, causing hyperammonemia." (PMID 35652051, 2022). "Here, the authors show that liver UDP-GlcNAc is increased during hyperammonemia, leading to O-GlcNAcylation of the rate-limiting ureagenesis enzyme CPS1, that enhanced ureagenesis and ammonia detoxification." (PMID 36064721, 2022). "Secondary hyperammonemia occurs during organic acidemias as a consequence of the accumulation of toxic substrates that impair CPS1 activity." (PMID 36064721, 2022). "In conclusion, by fine-tuned control of ammonia entry into ureagenesis, hepatic O-GlcNAcylation of CPS1 increases ammonia detoxification and is a novel target for therapy of hyperammonemia in both genetic and acquired diseases." (PMID 36064721, 2022). "CPS1D is the most severe of the UCDs, and individuals with complete inactivity of CPS1 rapidly develop hyperammonemia after birth." (PMID 32934962, 2020). "Carbamoyl phosphate synthetase I (CPS1) deficiency (CPS1D), is a rare autosomal recessive disorder, characterized by life-threatening hyperammonemia." (PMID 31507628, 2019). "CPS1 mutation can cause CPS1 deficiency (CPS1D), which causes hyperammonemia, neonatal death or mental retardation." (PMID 28272778, 2017). "In this context, the present study has expanded and deepened the original concept of the inhibitory effects of VPA on the activity of CPS1 and hyperammonemia." (PMID 28690671, 2017).
Hyperammonemia (continued). "CPS1 (carbamoyl phosphate synthetase I) encodes an ammonia ligase (DBGET: R00149) and deficiency of the CPS1 protein (MIM 608307) leads to hyperammonemia." (PMID 27884205, 2016). "The requirements were to generate a knock-in (KI) murine model in which adult size could be achieved, some residual endogenous Cps1 activity was present, and it simultaneously had at least mild hyperammonemia and amino acid derangements." (PMID 40421838, 2025). "Furthermore, SIRT5 activates the key urea cycle enzyme CPS1 through deacetylation, enhancing ammonia detoxification, whereas SIRT5 deficiency compromises CPS1 activity and leads to hyperammonemia under stress conditions." (PMID 41301698, 2025). "A recent study has reported that the O-GlcNAcylation level of CPS1 is elevated in hyperammonemia." (PMID 36768465, 2023). "Importantly, CPS1 ko mice die from hyperammonemia within 24 h after birth, and this enzyme catalyzes the conversion of ammonia to carbamoyl phosphate, i.e., the initial step in the urea cycle." (PMID 36674967, 2023). "Patients with defects in the function or expression of CPS1 suffer from hyperammonemia." (PMID 20040084, 2009). "Sustained hyperammonemia may be a direct consequence of low circulating acetyl-CoA levels, which is required for the formation of N-acetyl-glutamate, an essential urea cycle cofactor that allosterically regulates CPS1." (PMID 38013089, 2023). "Likewise, the reduced ammonium content could also be a consequence of reduced cell death, as urea cycle enzymes’ Cps1 and Otc mRNA expression and activities were reduced by the anti-miR-873-5p, despite reducing hepatic hyperammonemia." (PMID 35624761, 2022). "Hepatic protein expression of the UCEs, OTC, CPS1, and GLUD1 were significantly down-regulated in hyperammonemia, which was restored upon treatment with OP and TAK-242." (PMID 40053595, 2025). "In conclusion, our data show that hepatic O-GlcNAcylation enhances CPS1 catalytic efficiency for ammonia and promotes ureagenesis, thus indicating OGA as a novel therapeutic agent for therapy of both genetic and acquired diseases resulting in hyperammonemia." (PMID 36064721, 2022). "Hyperammonemia in Nags−/− mice expressing E354A mNAGS suggests that production of NAG in these mice is not sufficient for activation of CPS1 and normal urea production." (PMID 33574402, 2021). "It is very interesting that low CPS1 expression and hyperammonemia have been measured in Non-Alcoholic Steato Hepatitis (NASH) and Non-Alcoholic Fatty Liver Disease (NAFLD), which are very common diseases worldwide." (PMID 32498414, 2020).
hepatocellular carcinoma (23 papers, 2013 to 2026). A malignant tumor that arises from hepatocytes. "Low expression of ammonia-detoxifying carbamoyl phosphate synthase-1 is associated with worse overall survival of patients with hepatocellular cancer." (PMID 40163355, 2025). "In hepatocellular carcinoma, reduced expression of CPS1 is linked to hypermethylation of the promoter and is related to reduced survival and lymphatic invasion." (PMID 33915902, 2021). "By contrast, CPS1 down-regulation is noted in hepatocellular carcinoma, gastric adenocarcinoma and adenocarcinoma of the small intestine." (PMID 37443694, 2023). "CPS1 was thought to be involved in metabolic reprogramming in hepatocellular carcinoma, thus affecting the occurrence of tumors." (PMID 37033934, 2023). "Very recently, CPS1 downregulation of CPS1 expression in hepatocellular carcinomas and a further reduction in recurrent tumors and distant metastases was reported." (PMID 35008510, 2021). "CPS1 has been demonstrated to be downregulated in hepatocellular carcinoma by hypermethylation of the CPS1 promoter, whereas CAD mRNA levels were increased in HCC tissue." (PMID 33670206, 2021). "Hypermethylation of CPS1 accompanied by its downregulated expression was detected in hepatocellular carcinoma." (PMID 30967136, 2019). "This indicates that SPP2, LECT2, CPS1, and Ribokinase exert tumor suppressive effects in hepatocellular carcinoma." (PMID 31849319, 2019). "In this report, we created a CPS1‐tdtomato reporter cell system via CRISPR in a hepatic carcinoma cell line, HepG2, and an immortalized hepatic cell line, LO2." (PMID 28557353, 2017). "The expressions of CPS1 and P-CK in various hepatoma cell lines were firstly analyzed by flow cytometry." (PMID 24763545, 2014). "Altered expression of CPS1 was demonstrated in gastric cancer, hepatocellular carcinoma and small-intestinal adenocarcinoma, but there are no data on glial tumors published so far." (PMID 24358143, 2013). "Studies have demonstrated that CPS1 is downregulated in hepatocellular carcinoma and that its decline could lead to poor survival." (PMID 35557945, 2022). "The downregulation of CPS1 was related to unfavorable survival in hepatocellular carcinoma." (PMID 35251577, 2022). "CPS1 was discovered as the target of the hepatocyte paraffin 1 (HepPar1) antibody, which is most often used by pathologists to differentiate hepatocellular carcinoma from metastases, as it is highly expressed in cells of hepatocellular origin, whereas other organs only show low expression levels." (PMID 33670206, 2021). "SPP2 was co-expressed with LECT2, CPS1, and Ribokinase in hepatocellular carcinoma." (PMID 31849319, 2019). "Interestingly, in a subtype of hepatocellular carcinoma (HCC) where CPS1 expression is low, cells exhibit elevated ammonia levels, which subsequently activate pathways like AMPK-FOXM1 axis, enhancing lipid oxidation and ATP production to fuel tumor growth." (PMID 41356199, 2026). "Schematic diagram of NFIB promoting chemo-induced hepatocellular carcinoma by affecting urea cycle rate-limiting enzymes ASS1 and CPS1." (PMID 35655758, 2022). "During the transformation of hepatocytes into hepatoma cell, the regulatory effect of NFIB on ASS1 and CPS1 changed." (PMID 35655758, 2022). "In hepatoma cell line HepG2, and immortalized hepatic cell line LO2, carbamoyl phosphate synthetase 1 (CPS1) gene, the first enzyme of ammonia‐eliminating urea cycle, was labelled with fluorescence protein via CRISPR/Cas9 system." (PMID 28557353, 2017). "Interestingly, isoform switching between CPS1 and CPSII (via carbamoyl-phosphate synthetase 2, aspartate transcarbamylase, and dihydroorotase) occurs in hepatocellular carcinoma (HCC) to support pyrimidine synthesis and cell proliferation." (PMID 38013089, 2023). "We found that knockdown of NFIB can only augment the expression of CPS1 and ASS1 in normal hepatocyte but not in hepatoma cell, implying its stage-specific effect." (PMID 35655758, 2022).
hepatocellular carcinoma (continued). "Regulation of cAMP-PKA-CREB/ATF1 signaling represents a non-canonical function of CPS1, and targeting of the PKA-CREB/ATF1 axis may improve the therapeutic effects of aspirin in hepatocellular carcinoma." (PMID 35008510, 2021).